LINC02207 (long independently transcribed non-coding RNA 2207)
Synonyms: LINC01580
Gene: Long non-coding RNA gene on chromosome 15 (93,835,490 to 93,984,150, forward strand). Ensembl gene ENSG00000258476.
Diseases named in the same sentence as LINC02207 in open-access papers:
LINC02207 is named in the same sentence as 3 diseases in open-access papers, as found by Europe PMC text mining. Sharing a sentence is not in itself a finding about the gene and the disease. The quoted sentences say what the papers report.
COVID-19 (1 paper, 2021). A disease caused by infection with severe acute respiratory syndrome coronavirus 2. "It has been observed that increased level of LINC02207, LINC01127 was associated with the severe COVID-19 group, whereas LINC02084, LINC02446, LINC00861, LINC01871, and ANKRD44-AS1 were associated with the mild COVID-19 group." (PMID 34940755, 2021).
ovarian carcinoma (1 paper, 2021). A malignant neoplasm originating from the surface ovarian epithelium. "The data showed that compared with adjacent normal cases, LINC01722 was upregulated, whereas AC134312.1, AL133467.1, CHRM3-AS2, and LINC02207 were downregulated in ovarian carcinoma." (PMID 33997040, 2021). "We further observed that AC134312.1, AL133467.1, CHRM3-AS2, and LINC02207 were downregulated, whereas LINC01722 was upregulated in ovarian carcinoma compared with normal tissues." (PMID 33997040, 2021).
LINC02207 also shares sentences with these, for which no sentence is quoted: Sepsis (1 paper).